ITGA1 (integrin subunit alpha 1)
Description:
Integrin alpha-1/beta-1 is a receptor for laminin and collagen. It recognizes the proline-hydroxylated sequence G-F-P-G-E-R in collagen. Involved in anchorage-dependent, negative regulation of EGF-stimulated cell growth.
Synonyms: CD49a; VLA1
Tractability: Small molecule: a high-quality ligand is known. Antibody: its Gene Ontology location is reachable by antibodies, with high confidence; UniProt predicts a signal peptide or a membrane-spanning region. PROTAC: ubiquitination databases record sites on it; its protein half-life has been measured; a small molecule that binds it is known.
Target class: Membrane receptor
Gene: Protein-coding gene on chromosome 5 (52,787,916 to 52,959,209, forward strand). Ensembl gene ENSG00000213949.
Subcellular location: Membrane
Subcellular location (Human Protein Atlas): Endoplasmic reticulum
Pathways (Reactome):
Developmental Biology: CHL1 interactions; Other semaphorin interactions
Extracellular matrix organization: Integrin cell surface interactions; Laminin interactions
Hemostasis: Platelet Adhesion to exposed collagen
Muscle contraction: Smooth Muscle Contraction
Gene Ontology:
Molecular function: collagen binding involved in cell-matrix adhesion; phosphatase activator activity; protein binding; protein phosphatase binding; collagen binding; signaling receptor activity; signaling receptor binding
Biological process: cell-matrix adhesion; negative regulation of cell population proliferation; cell-cell adhesion; integrin-mediated signaling pathway; negative regulation of epidermal growth factor receptor signaling pathway; cell adhesion; cell chemotaxis; neuron projection morphogenesis; positive regulation of MAPK cascade; positive regulation of neuron apoptotic process; vasodilation
Cellular component: cell surface; extracellular exosome; focal adhesion; integrin alpha1-beta1 complex; membrane; integrin complex; plasma membrane; acrosomal vesicle; basal part of cell; external side of plasma membrane; perikaryon
Genetic constraint (gnomAD): Loss-of-function variants: 42 observed, 70.43 expected, observed/expected ratio (o/e) 0.6, 90% interval 0.47 to 0.77. The upper end of that interval is the gene's LOEUF score, 0.77, which puts it in group 3 of 6, group 1 being the genes least tolerant of losing a copy. Missense variants: 879 observed, 925.5 expected, observed/expected ratio (o/e) 0.95, 90% interval 0.9 to 1. Synonymous variants: 336 observed, 330.53 expected, observed/expected ratio (o/e) 1.02, 90% interval 0.93 to 1.11.
Homologues: Orthologues: chimpanzee ITGA1 (99% identical), macaque ITGA1 (98% identical), rabbit ITGA1 (91% identical), dog ITGA1 (91% identical), pig ITGA1 (90% identical), mouse Itga1 (88% identical), guinea pig ITGA1 (88% identical), rat Itga1 (87% identical), tropical clawed frog itga1 (62% identical), zebrafish itga1 (52% identical), Drosophila melanogaster mew (21% identical), Caenorhabditis elegans ina-1 (20% identical), and 5 more. Paralogues in human: ITGA2 (40% identical), ITGA11 (38% identical), ITGA10 (35% identical), ITGAL (27% identical), ITGAM (27% identical), ITGAX (26% identical), ITGAD (25% identical), ITGAE (24% identical), ITGA9 (21% identical), ITGA4 (21% identical), ITGA7 (20% identical), ITGA3 (20% identical), and 5 more.
Diseases named in the same sentence as ITGA1 in open-access papers:
ITGA1 is named in the same sentence as 140 diseases in open-access papers, as found by Europe PMC text mining. Sharing a sentence is not in itself a finding about the gene and the disease. The quoted sentences say what the papers report.
melanoma (17 papers, 2015 to 2025). A malignant, usually aggressive tumor composed of atypical, neoplastic melanocytes. "Recent studies indicate that ITGA1 is associated with melanoma proliferation via the regulation of miR-3065-5p." (PMID 34660316, 2021). "Thus, considering all these results, we show here that, at least in our hands, in A375 melanoma cells, ITGA1, PCDH2, and TRP-1 are phenotypically similar with the novel EDEM2 substrate, ST-TYR." (PMID 34332121, 2021). "In addition, as a mediator of cell-cell and cell-matrix adhesion, ITGA1 was differentially expressed in melanoma samples." (PMID 34660316, 2021). "PCDH2 and ITGA1 are adhesion proteins with crucial roles in melanoma invasion." (PMID 34332121, 2021). "Interestingly, while integrin alpha one (ITGA1) is frequently upregulated in PDAC, we also note that there are malignancies in which ITGA1 is more frequently overexpressed (e.g., Melanoma, Prostate, Bladder, Liver and Myeloma)." (PMID 28855593, 2017). "In melanoma, IL-15 expression positively correlates with TRM abundance and higher mRNA levels of ITGAE (CD103), ITGA1 (CD49a), and CD69, reinforcing its role in maintaining residency and effector potential." (PMID 41479900, 2025). "To confirm some of the identified potential substrates, we monitored the candidates, PCDH2, ITGA1, and the melanoma antigen TRP-1, expression, and intracellular distribution in A735-ST-TYR melanoma cells with either overexpressed or downregulated EDEM2 protein expression." (PMID 34332121, 2021). "In addition, miR-3065-5p functions as an antitumor miRNA to inhibit the proliferation of melanoma cells by targeting the HIPK1 and ITGA1 genes." (PMID 34656128, 2021).
pancreatic cancer (14 papers, 2017 to 2025). "We discovered that integrin alpha 1 (ITGA1) is frequently upregulated in pancreatic cancers and associated precursor lesions." (PMID 28855593, 2017). "ITGA1 is a pre-malignant biomarker, which usually fosters therapy resistance and metastatic potential in pancreatic cancer." (PMID 35053843, 2022). "For example, suppression of ITGA1 expression is known to reduce the migration and invasion of hepatocellular carcinoma cells and pancreatic cancer cells." (PMID 34503200, 2021). "For instance, increased integrin subunit alpha 1 (ITGA1) actuated gemcitabine resistance by cooperating with TGF-β in pancreatic cancer." (PMID 32232000, 2020). "Although previous data reported that H19 overexpression reduced ITGB3, ITGB5, and ITGA5 in bladder cancer cells and increased ITGB1 and ITGA1 in pancreatic cancer cells, the molecular mechanism by which H19 regulates integrin was not elucidated." (PMID 31426484, 2019). "Testing additional patient‐derived pancreatic cancer cells reveals particular genes (ITGA1,TNFAIP2,COMMD7,RAB3D) that respond to APE1 knockdown similarly across all the cell lines." (PMID 28922540, 2017). "Notably, ITGA1 has been identified as a pro-malignant biomarker in pancreatic cancer, promoting drug resistance and metastatic potential." (PMID 41031085, 2025). "ITGA1 is highly expressed in pancreatic cancer, colorectal cancer, and GC." (PMID 33335550, 2020). "Expression of ITGA1-specific collagens within the pancreatic cancer microenvironment significantly correlates with indicators of poor patient prognosis, and depleting ITGA1 from PDAC cells revealed that it is required for collagen-induced tumorigenic potential." (PMID 28855593, 2017). "This identified PEAK1, BMPR2, COL4A1 and ZEB1 as ITGA1 co-expressors in pancreatic cancer and suggested that ITGA1 may play a role in regulating TGFβ responses in pancreatic cancer." (PMID 28855593, 2017). "Since mesenchymal cell morphology and gene expression signatures are commonly associated with the metastatic potential of pancreatic cancer cells, we evaluated whether collagen could affect the morphology, spreading and attachment of PDAC cells in an ITGA1-dependent manner." (PMID 28855593, 2017). "Most important was the bottleneck gene (Integrin alpha-1, ITGA1) between two of the major communities, which is a pre-malignant biomarker that promotes treatment resistance and metastasis potential in pancreatic cancer." (PMID 33669233, 2021). "Notably, this pro-metastatic effect of ITGA1 was much less apparent in the absence of TGFβ/collagen pre-treatment and co-xenografting, demonstrating a TGFβ/collagen microenvironment-specific role for ITGA1 in pancreatic cancer progression." (PMID 28855593, 2017).
psoriasis (14 papers, 2020 to 2025). An autoimmune condition characterized by red, well-delineated plaques with silvery scales that are usually on the extensor surfaces and scalp. "A study revealed that after blocking the interaction between α1β1 integrin (ITGA1) and collagen, epidermal T cells accumulate and prevent psoriasis immunopathology." (PMID 40756258, 2025).
hepatocellular carcinoma (13 papers, 2017 to 2026). A malignant tumor that arises from hepatocytes. "NK cells infiltrating Hepatocellular Carcinoma (HCC) may express residency markers such as Integrin Subunit Alpha 1 (CD49a) that have been associated with nurturing functions in the decidua, and characterized by the production of angiogenic factors as well as loss of cytotoxicity." (PMID 38107324, 2023). "ITGA1 expression depletion resulted in the suppression of migration and invasion in hepatocellular carcinoma cells." (PMID 40001606, 2025). "In hepatocellular carcinoma (HCC), METTL6 depletion inhibits cell growth, colony formation, migration, invasion, and cell adhesion and reduces the expression levels of cell adhesion proteins such as ITGA1, SPON1, and CLDN14." (PMID 41501031, 2026).
breast carcinoma (10 papers, 2015 to 2025). "ITGA1-coded integrin α1 protein upregulated following the expression of estrogen receptor β, a marker of breast cancer." (PMID 35414113, 2022). "It was recently shown that ITGA1 is a differentially expressed-aberrantly methylated gene in breast cancer, providing a possible independent functional role of its hypermethylation in BC35." (PMID 33500458, 2021). "In basal-like breast cancer, we found that a low WWOX/HIF1A ratio is associated with particularly aggressive disease because it promotes EMT via ZEB1 and ADAM9, facilitates ECM remodelling via MMP2 and ITGA1, and enables immune evasion via NOTCH1 and TLR4." (PMID 41007296, 2025). "In this regard, ITGA1 was found to mediate signals in promoting cancer growth of lung cancer cells in the mice model 24, and blocking ITGA1 could reduce cell invasion and adhesion in a mice breast cancer model." (PMID 32071551, 2020). "In this study, we have identified high frequencies of cancer specific abnormal hypermethylation of the parts of promoter regions of integrin ITGA1, ITGA4, ITGA9, and nidogen NID1, NID2 genes in breast cancer." (PMID 33500458, 2021). "In this regard, we demonstrate here that unlike in breast cancer, where TGFβ cooperates with ITGB3-specific ECM proteins, TGFβ preferentially cooperates with ITGA1-specific collagens in PDAC to promote EMT, therapy resistance and metastasis." (PMID 28855593, 2017).
colorectal cancer (9 papers, 2017 to 2025). A primary or metastatic malignant neoplasm that affects the colon or rectum. "Previous literature findings also demonstrate a strong correlation between ITGA1 (Integrin subunit alpha 1) and c-Myc expression in colorectal cancer cells." (PMID 38509115, 2024). "In individuals with colorectal cancer, the serum concentration of ITGA1 was also found to be significantly higher compared with that in healthy individuals and showed a significant association with metastatic (tumour, node, metastasis [TNM]) stage." (PMID 38413438, 2024). "We have recently shown that the integrin α1 protein and transcript (ITGA1) are present in a large proportion of colorectal cancers (CRC) and that their expression is controlled by the MYC oncogenic factor." (PMID 28933766, 2017). "Together, these findings could in part explain the small size of sh-ITGA1 tumors relative to the control tumors and suggest a role for the α1β1 integrin in the progression of colorectal cancer." (PMID 28933766, 2017). "Indeed, ITGA1 protein was up-regulated in 65% of colorectal cancers." (PMID 32071551, 2020). "Moreover, we also examined the concentration of ITGA1 in the sera of CRC patients and analyzed the correlation with clinicopathological features, stages and colorectal neoplasms markers of colorectal cancer." (PMID 32071551, 2020).
glioma (8 papers, 2019 to 2025). A benign or malignant brain and spinal cord tumor that arises from glial cells (astrocytes, oligodendrocytes, ependymal cells). "We additionally analyzed the expression of a panel genes (Angpt2, Sox4, Vegfa, Kdr, Itga1, Mcam, Notch4 and Ets1) associated with vascular abnormality in ECs using RNA extracted from total glioma tumor tissues from control and treated mice." (PMID 34867089, 2021). "TA-MAC, on the other hand, expressed significantly higher levels of Itga4 and Itga1 which have recently been reported to be robust markers for glioma-associated macrophages." (PMID 30602457, 2019). "This activity promotes glioma progression and resistance by augmenting integrin subunit alpha 1 (ITGA1) gene expression by activating the PI3K/AKT pathway." (PMID 39877636, 2025). "To further reveal the biological function of ITGA1 in glioma progression, we screened for genes that were correlated with ITGA1 by differential expression analysis." (PMID 39502752, 2024). "ITGA1 was obviously higher in grade 3 than in grade 2 glioma, and it was upregulated significantly in IDH1 wild-type and 1p19q non-codeficient LGG as compared to IDH mutant and 1p19q codeficient LGG." (PMID 39502752, 2024). "ITGA1 expression was altered the glioma immune environment and promoted the expression of immune checkpoint-related genes and immune cell infiltration." (PMID 39502752, 2024). "qPCR assay showed that ITGA1 mRNA level was increased with the increase of glioma grades, and it was relatively higher in glioma cell lines than in HA1800, a human astrocyte cell line." (PMID 39502752, 2024). "We first applied an immunoblotting assay to detect the expression level of ITGA1, and further verified the mRNA level by qPCR, indicating that the glioma cell lines with stably downregulated ITGA1 were successfully constructed." (PMID 39502752, 2024). "To confirm the increased expression of ITGA1 in glioma tissues, we performed qPCR and Western blot to measure the mRNA and protein levels of ITGA1 in our glioma cohort." (PMID 39502752, 2024). "This study indicates that hsa_circ_0110757 inhibits glioma cell apoptosis by sponging hsa-miR-1298-5p to promote ITGA1 expression." (PMID 33674567, 2021). "In summary, we found that hsa_circ_0110757 is overexpressed in TMZ-resistant glioma tissues and cells and can effectively sponge hsa-miR-1298-5p to increase the expression of ITGA1." (PMID 33674567, 2021). "It was found that hsa_circ_0110757 and ITGA1 are more highly expressed in TMZ-resistant glioma than in TMZ-sensitive glioma." (PMID 33674567, 2021). "In order to further investigate whether ITGA1 promotes the proliferation of tumor cells, we constructed glioma cell lines with stable downregulation of ITGA1 in LN229 and U251 cells, respectively." (PMID 39502752, 2024). "Further investigations are required to verify the role of ITGA1 in glioma progression." (PMID 39502752, 2024). "In vivo experiments showed that overexpression of ITGA1 promoted glioma cell invasion." (PMID 39502752, 2024). "In order to further verify whether the downregulation of ITGA1 would affect the clone formation ability of glioma cells, we performed clone formation assay, the results showed that it was significantly reduced after downregulation of ITGA1." (PMID 39502752, 2024). "However, it is less well known about the role of ITGA1 in gliomas and the relationship of ITGA1 with tumor immunity." (PMID 39502752, 2024). "In addition, we found that hsa_circ_0110757 facilitates TMZ resistance modulation by sponging hsa-miR-1298-5p, which inhibits Integrin subunit alpha 1 (ITGA1) expression by activating the PI3K/AKT pathway in glioma." (PMID 33674567, 2021). "Moreover, compared with TMZ-sensitive glioma tissues, immunohistochemical staining showed that ITGA1 was significantly elevated in TMZ-resistant glioma tissues." (PMID 33674567, 2021).
glioma (continued). "In addition, the correlations among hsa_circ_0110757, miR-1298-5p, and the ITGA1 protein levels were recognized in 32 glioma samples." (PMID 33674567, 2021). "Similarly, after known down of ITGA1, the invasion ability of glioma cells was inhibited." (PMID 39502752, 2024). "Thus, high expression of ITGA1 in gliomas significantly promoted the proliferation of glioma cells." (PMID 39502752, 2024). "Thus, ITGA1 may contribute to the malignant progression of glioma by altering immune microenvironment." (PMID 39502752, 2024). "At the molecular level, hsa_circ_0110757 can sponge hsa-miR-1298-5p to eliminate the suppressive effect of hsa-miR-1298-5p on ITGA1, which then excites the PI3K/AKT signaling pathway and inhibits apoptosis in glioma cells." (PMID 33674567, 2021). "Integrin α1 (ITGA1), a family member of integrins, is implied in the malignant development of cancers, but the fundamental role of ITGA1 has not been illustrated yet in glioma." (PMID 39502752, 2024). "Western blot analysis showed that ITGA1 was upregulated in glioma tissues compared to nontumor brain." (PMID 39502752, 2024). "Finally, by using gene correlation analysis, we found that the COL1A1, COL1A2, FN1, ITGA1, ITGB1, and ANXA1 genes may play a synergistic role in glioma patients." (PMID 35711921, 2022).
diabetes (6 papers, 2015 to 2024). "ITGA1 was also reported to be closely associated with diabetes and diabetic retinopathy." (PMID 35010640, 2021). "Moreover, a multivariate Cox regression analysis revealed that the baseline ITGA1 level was independently associated with re-hospitalisation (HR 2.331 [95% CI 1.387, 3.917], p=0.001) after adjusting for age, duration of diabetes, smoking, atrial fibrillation history and baseline creatinine levels." (PMID 38413438, 2024). "Furthermore, ITGA1 has been implicated in diabetes-related complications." (PMID 38413438, 2024). "In the comparison between the low-ITGA1 and high-ITGA1 groups, participants in the high-ITGA1 group were found to be older, had longer durations of diabetes, and had a higher proportion of atrial fibrillation, as well as lower proportion of arterial hypertension." (PMID 38413438, 2024). "Additionally, compared with the low-ITGA1 group, the high-ITGA1 group had a longer duration of diabetes and displayed higher levels of creatinine and NT-proBNP, along with lower levels of albumin." (PMID 38413438, 2024).
gastric cancer (6 papers, 2020 to 2025). A primary or metastatic malignant neoplasm involving the stomach. "In this study, we analyzed ITGA1 on a pan-cancer basis and revealed that ITGA1 was highly expressed in many kinds of cancer, including metastatic melanoma, lung cancer, HCC, and gastric cancer." (PMID 39502752, 2024).
ovarian carcinoma (6 papers, 2017 to 2023). A malignant neoplasm originating from the surface ovarian epithelium. "Moreover, ITGA1 downregulation has been associated with poor patient outcome and drug resistance in ovarian cancer." (PMID 32813746, 2020). "We demonstrate that in the mouse ID8 IP2 and human OVCA429/OVSAHO ovarian cancer cell lines, Notch3 signaling upregulates the collagen I receptor subunit, ITGA1." (PMID 32525899, 2020). "To confirm that Notch3IC also increases ITGA1 expression in human ovarian cancers, we overexpressed Notch3IC in two late-stage human ovarian cancer cell lines, OVCA429 and OVSAHO." (PMID 32525899, 2020). "Notch 3 activation was found to increase the expression of ITGA1 in ovarian cancer cells." (PMID 35053843, 2022). "Notch3IC-mediated increase of ITGA1 was also seen in two human ovarian cancer cells." (PMID 32525899, 2020). "The mRNA levels of ITGA1, ITGB1, ITGB3, and ITGB8 were found to be highly elevated in ovarian cancer tissues compared to those in normal ovarian tissues." (PMID 37596406, 2023). "Interestingly, DDR2 knockdown significantly abrogated COL11A1-induced FASN overexpression while ITGA1 knockdown only slightly reduced FASN expression (data not shown), suggesting that DDR2 might be the predominant receptor that mediates COL11A1-induced FASN expression in ovarian cancer cells." (PMID 32312965, 2020).